RNU5D-2P (RNA, U5D small nuclear 2, pseudogene)
Gene: Small nuclear RNA gene on chromosome 9 (132,421,641 to 132,421,690, forward strand). Ensembl gene ENSG00000252521.
Homologues: Orthologues: macaque U5 (92% identical), rabbit U5 (90% identical), macaque U5 (84% identical), dog U5 (78% identical), rabbit U5 (72% identical). Paralogues in human: RNU5A-8P (94% identical), RNU5E-4P (94% identical), RNU5E-6P (94% identical), RNU5B-4P (92% identical), RNU5B-2P (90% identical), RNU5B-3P (88% identical), RNU5E-10P (88% identical), RNU5E-9P (88% identical), RNU5A-4P (86% identical), RNU5B-6P (86% identical), RNU5E-7P (86% identical), RNU5E-8P (86% identical), and 13 more.